PPP1CB (protein phosphatase 1 catalytic subunit beta)
Diseases named in the same sentence as PPP1CB in open-access papers (continued):
Sharing a sentence is not in itself a finding about the gene and the disease.
craniosynostosis (1 paper, 2024). Craniosynostosis is defined as the premature fusion of one or more cranial sutures leading to secondary distortion of skull shape resulting in skull deformities with a variable presentation. "Craniosynostosis has been described in individuals with pathogenic variants in other genes of the RAS/MAPK pathway including BRAF, KRAS, PPP1CB, SHOC2, PTPN11, RAF1, and HRAS." (PMID 37774117, 2024).
epilepsy (1 paper, 2017). A brain disorder characterized by episodes of abnormally increased neuronal discharge resulting in transient episodes of sensory or motor neurological dysfunction, or psychic dysfunction. "The brown module has 53 hub genes, including genes associated with dopaminergic signaling (GNB1, GSK3B), long-term potentiation (PPP1CB), opioid signaling (PPP2CA, PPP3CA, PPP3R1), epilepsy (SYN1), and Parkinson’s disease (SNCA)." (PMID 28710498, 2017).
Epileptic spasm (1 paper, 2018). A sudden flexion, extension, or mixed extension-flexion of predominantly proximal and truncal muscles that is usually more sustained than a myoclonic movement but not as sustained as a tonic seizure. "Herein, we report a male infant with a PPP1CB mutation who presented not only with typical clinical features of NSLH2 but also epileptic spasms that were almost refractory to conventional antiepileptic drugs (AEDs)." (PMID 30236064, 2018).
infantile spasms (1 paper, 2018). A rare epilepsy syndrome characterized by onset of epileptic spasms in infants between 2 and 12 months of age, and rarely up to 24 months. "Moreover, the first case of PPP1CB-related infantile spasms." (PMID 30236064, 2018).
loose anagen hair syndrome (1 paper, 2018). "The PPP1CB gene has been associated with Noonan syndrome-like disorder with loose anagen hair syndrome (NSLH2)." (PMID 30236064, 2018).
osteosarcoma (1 paper, 2020). A usually aggressive malignant bone-forming mesenchymal neoplasm, predominantly affecting adolescents and young adults. "Surprisingly, however, endogenous NUAK1 localized mainly to the nucleus of U2OS osteosarcoma cells; the staining occurred in a speckled pattern that partly co-localized with the nuclear pool of the protein phosphatase catalytic subunit beta (PPP1CB)." (PMID 32006464, 2020).
polymyalgia rheumatica (1 paper, 2018). A syndrome characterized by pain, stiffness, and tenderness of the proximal muscle groups including the shoulder, pelvic girdle and the neck. "PPP1CB and EIF4A3 were shared by both jaw claudication and a background history of Polymyalgia Rheumatica (PMR)." (PMID 30037347, 2018).
cancer (21 papers, 2009 to 2025). A tumor composed of atypical neoplastic, often pleomorphic cells that invade other tissues. "Protein phosphatase-1 catalyzed subunit β (PPP1CB) is related to the generation and differentiation of adipocytes, which is relatively scarce in cancer studies." (PMID 36741702, 2022). "Most of these APA regulators were specifically upregulated in seven cancer types, while PPP1CB, PCF11, and PABPC1 were significantly downregulated in ESCC." (PMID 35654793, 2022). "PPP1CB plays a vital role in regulating the cytoskeleton network and cell migration, processes germane to cancer invasion and metastasis." (PMID 34125004, 2021). "We observed that PPP1CB-TAI was present in each cancer type." (PMID 41273175, 2025). "Next, we investigated the PPP1CB isoform that was predicted to be antigenic, i.e. the Tumor Antigenic Isoform in PPP1CB or PPP1CB-TAI, in bulk RNAseq data from 6 557 solid tumors in 16 cancer types, as well as 594 corresponding normal tissues." (PMID 41273175, 2025). "Using beta-binomial GLM, we observed a significant positive correlation between PPP1CB-TAI and IFN-γ in 8 of 16 cancer types (likelihood ratio test, P < 0.05)." (PMID 41273175, 2025). "Particularly, ESRP1 was involved in response to ICB, while a cancer cell-specific ASE, i.e. PPP1CB-TAI, could serve as a potential tumor antigen predictive of response to ICB." (PMID 41273175, 2025). "Enhancing actomyosin contractility through PPP1R12A or PPP1CB depletion led to nuclear rupture in HeLa, MDA-MB-231, A549, SiHa and HT1080 cancer cells but had little effect on nuclear integrity in telomerase-immortalized hTERT RPE-1 cells and BJ-5ta primary fibroblasts." (PMID 28737169, 2017). "We found that FYN and PPP1CB were negatively correlated with RNAss, while PPP1CC was positively correlated with RNAss, which indicated that prognostic genes might have a relationship with cancer cell sensitivity or resistance to chemotherapy treatment." (PMID 33850056, 2021). "To determine whether MYC and its putative interactor, PP1/PNUTS, are both expressed in cancer, we examine the amplification status of the MYC gene, as well as genes of the PP1/PNUTS holoenzyme (PPP1CA, PPP1CB, PPP1CC, and PPP1R10) in The Cancer Genome Atlas (TCGA) datasets." (PMID 30158517, 2018).
tumor (18 papers, 2004 to 2025). "The catalytic subunit of PP1 is encoded by PPP1CA, PPP1CB, and PPP1CC (protein name PP1γ), and the roles of each subunit in tumor development are inconsistent." (PMID 40626009, 2025). "Phosphorylation of a PPP1CB inhibitor can promote contractile actomyosin mechanisms and accelerate tumor metastasis." (PMID 34125004, 2021). "As a regulator of endothelial cell migration, PPP1CB may be an effective target for anti-angiogenic therapy and inhibition of tumor growth." (PMID 34125004, 2021). "Additionally, it has been shown that PPP1CB is related to tumor cell migration and metastasis, PPP1CB can promote actomyosin contraction and accelerate tumor metastasis when the PPP1CB inhibitor is phosphorylated." (PMID 34125004, 2021). "As one of the catalytic subunits of PP1, PPP1CB has been found to be critical to the dephosphorylation of myosin light chain, frequently involved in regulating the cytoskeleton network and the process of cell migration, and closely related to tumor invasion and metastasis." (PMID 39286117, 2024). "Therefore, genes VEGFA, ANXA1, HSP90B1, PSMA7, PRDX6, and PPP1CB may be new targets for anti-tumor effects in the future." (PMID 36741702, 2022). "We investigated the expression levels of PPP1CB in tumor samples from PAAD patients and determined the correlation of PPP1CB expression with clinical outcomes of PAAD patients." (PMID 34125004, 2021). "A PPP1CB immunohistochemical staining was performed using a tissue microarray (TMA), consisting of tumor samples collected from 91 patients with PAAD (88 of which contained matched paracancerous tissues)." (PMID 34125004, 2021). "While the analysis of the methylation of Spinophilin showed increased methylation, the analysis of PPPCs subunits methylation showed a decreased methylation mean, in tumors vs. non-tumor samples, in PPP1CA and PPP1CB, and increased methylation mean in PPP1CC." (PMID 29285244, 2017). "When exploring public bulk RNAseq data from five clinical trials involving ICB, we could confirm that PPP1CB-TAI significantly predicted response independently of TMB, confirming its role as a potential tumor antigen." (PMID 41273175, 2025). "In addition, the expression of PPP1BC, PPP1CC and RAC1 was correlated with the tumor stage (P < 0.05); the expression of PPP1CC and SPP1 was correlated with age (P < 0.05); the expression of PPP1CB was correlated with gender (P < 0.05)." (PMID 33850056, 2021).
infection (5 papers, 2016 to 2025). The state of being infected such as from the introduction of a foreign agent such as serum, vaccine, antigenic substance or organism. "In agreement with the MS data, infection with H. pylori or 10 min of treatment with cytokines led to the dissociation of PPP1CA, PPP1CB and PPP1CC from TAK1." (PMID 29581850, 2018). "The proteasome has a recognized role in antigen presentation during infection but a role in direct bacterial killing has only very recently been described, coordinated by PSME3 and effected by proteasome cleaved antimicrobial peptides including PPP1CB, both prioritized in our analysis." (PMID 40447280, 2025).
PPP1CB also shares sentences with these, for which no sentence is quoted: Sepsis (3 papers); cardiofaciocutaneous syndrome (2); chronic lymphocytic leukaemia (2); colorectal cancer (2); Costello syndrome (2); gastric cancer (2); heart failure (2); Hypertension (2); lung carcinoma (2); non-small cell lung carcinoma (2); prostate carcinoma (2); acute megakaryoblastic leukemia (1); adrenocortical carcinoma (1); anorexia nervosa (1); Anxiety (1); bipolar disorder (1); breast tumor (1); cardiomyopathy (1); cervical carcinoma (1); Cowden syndrome (1); cyst (1); depression (1); developmental delay (1); embryonal rhabdomyosarcoma (1); Epileptic encephalopathy (1); head and neck cancer (1); Hyperhidrosis (1); influenza (1); Intellectual disability (1); invasive breast carcinoma (1).
A further 18 diseases each share a sentence with PPP1CB in 1 paper.